BRCA2 (BRCA2 DNA repair associated)
Diseases named in the same sentence as BRCA2 in open-access papers (continued):
Sharing a sentence is not in itself a finding about the gene and the disease.
medulloblastoma (continued). "Additionally, biallelic mutations in FANCD1/BRCA2 and FANCN/PALB2 are associated with neuroblastoma, medulloblastoma, and Wilms Tumor." (PMID 40739565, 2025). "However in two pediatric medulloblastoma patients with mutations in DNA repair genes (PALB2 and BRCA2) chemotherapy inducted grade 4 side effects were reported." (PMID 28376765, 2017). "In addition to the BRCA2 6174delT, the medulloblastoma cells had amplification of MYC, deletion at Xp11.2, and isochromosome 17, but no structural variations or overexpression of GFI1 or GFI1B." (PMID 26380221, 2015). "We identified two point mutations in KDM6A, which had not previously been identified in medulloblastomas, and validated germline mutations in BRCA2, RAD51D and ATM, which are all involved in DNA repair of double-stranded breaks as well as hereditary cancer syndromes." (PMID 37576901, 2023). "Biallelicmutations in BRCA2 (also known as FANCD1) areidentified in around 3-5% of FA cases and are associated with a high risk ofaggressive embryonal tumors in early childhood stages (mostly medulloblastomas andnephroblastomas) and/or acute leukemia (Reidet al., 2005; Meyeret al., 2014)." (PMID 31067289, 2019). "In view of the high incidence of BRCA2 6174delT carrier state in some populations (e.g., Ashkenazi Jews, ~0.9%), it will also be important to examine if children from families carrying the heterozygous BRCA2 6174delT mutation have higher incidence of medulloblastoma than non-carriers." (PMID 26380221, 2015).
medulloblastoma (continued). "Interestingly, the UW-228-2 medulloblastoma cell line showed almost no anti-BRCA2 antibody reactivity, while the other medulloblastoma cell line, D283MED, had BRCA2 protein amounts comparable to the CHLA-02-ATRT, LN229 GBM, and 293T cell lines." (PMID 26380221, 2015).
hereditary cancer syndromes (30 papers, 2009 to 2025). "Several genes critical in repairing DNA double-strand breaks (DSB) have been linked to hereditary cancer syndromes and infertility in both men and women (e.g. BRCA2, FANCM, XRCC2)." (PMID 40060932, 2025). "We described a case of an EO‐SBA patient with both somatic and germline BRCA2 variants, indicating a role of the BRCA2‐related hereditary cancer syndrome in the SBA development." (PMID 40205657, 2025). "However, effective identification of mutated high-risk cancer genes such as BRCA1 and BRCA2 depends on the availability of and access to genetic counseling and testing for people at high risk of a hereditary cancer syndrome." (PMID 39710803, 2024). "In the BRCA1 and BRCA2 genes, SNVs such as rs16942 and rs1799944 have been linked to increased BC risk, further underscoring the importance of comprehensive genetic analysis in managing hereditary cancer syndromes." (PMID 39710803, 2024). "Although BRCA2 mutations, both somatic and germline, have been recently described in SBAs, direct evidence of BRCA2 inactivation in SBA tumor tissue of patients with BRCA2‐related hereditary cancer syndrome is still very limited." (PMID 40205657, 2025). "Ovarian epithelial tumors are an hallmark of hereditary cancer syndromes which are related to the germ-line inheritance of cancer predisposing mutations in BRCA1 and BRCA2 genes." (PMID 19825178, 2009). "Studies like these provide the basis for the improvement of collective knowledge of genetic risk of C-terminal variants in BRCA2 and will continue to be essential to reducing the number of VUS and expanding the ability for accurate genetic counseling of hereditary cancer syndromes." (PMID 33503928, 2021). "More recently, data from a large international consortium of families with hereditary cancer syndromes associated with BRCA germline mutations demonstrated that the relative risk (RR) of PDAC was 2.36 (95% CI, 1.51–3.68) for BRCA1 and 3.34 (95% CI, 2.21–5.06) for BRCA2." (PMID 35805011, 2022). "Individuals with proven hereditary cancer syndrome (HCS) such as BRCA1 and BRCA2 have elevated rates of ovarian, breast, and other cancers." (PMID 35877228, 2022). "Regarding the PC group, three patients (representing 9.3% of the PC cohort and 50% of the PC patients with germline test done) were diagnosed with an inherited syndrome: two HBOC (1 BRCA2 and 1 PALB2) and one ATM hereditary cancer syndrome (ATM)." (PMID 32842532, 2020). "Despite negative BRCA1 and BRCA2 test results, in certain cases, clinicians often remain suspicious of another hereditary cancer syndrome due to the family history of cancer." (PMID 28281021, 2017). "Hereditary MTC is a different clinical context than other hereditary cancer syndromes (e.g., BRCA1, BRCA2), where penetrance is significantly lower, the genetic test can yield ambiguous results, and the effectiveness and perceived benefits of "treatment" is unknown or has significant side effects." (PMID 21436957, 2011).
metastatic prostate carcinoma (30 papers, 2008 to 2026). A carcinoma that arises from the prostate gland and has spread to other anatomic sites. "Metastatic prostate cancer with a BRCA2 mutation is associated with aggressive clinical behavior and poor outcomes with standard systemic therapy." (PMID 41669591, 2026). "Several gene mutations, including PIK3CA, LRP6, LRRK2, and BRCA2, were found to be associated with metastatic prostate cancer and BCR." (PMID 40660132, 2025). "The case in question involved a patient with metastatic prostate cancer who had a BRCA2 mutation in the source of their DNA repair." (PMID 39364320, 2024). "Collectively, these results highlight that individual copy number-based features from WES are insufficient to reliably predict BRCA2 deficiency in metastatic prostate cancer." (PMID 36914848, 2023). "The genes containing the highest number of protein-truncating variants in men with metastatic prostate cancer were BRCA2, ATM, and NBN." (PMID 33804961, 2021). "A male patient with metastatic prostate cancer and a BRCA2 mutation has responded well to a PARP1 inhibitor (A Tutt, J De Bono, personal communication)." (PMID 18577985, 2008). "Some of them have been described as predictors of therapy response or ways of helping to guide therapies such as TMPRSS2-ERG fusion, PTEN status, presence of AR-V7 splice variant, mutations in DNA-repair genes such as BRCA2/1, etc. in metastatic prostate cancer patients." (PMID 35207452, 2022). "We conclude that BRCA2 mutated metastatic prostate cancers may present in an advanced stage with relatively low PSA." (PMID 36362213, 2022). "The PROREPAIR-B study showed that patients with metastatic prostate cancer and germline BRCA2 mutations exhibited a shorter time to developing castration resistance compared with non-carriers, suggesting that tumors in BRCA2 mutation carriers may be less reliant on AR signaling pathways." (PMID 39859392, 2025). "The current study within a busy clinical urogenital service supports the major involvement of BRCA2 in metastatic prostate cancer with a combined sBRCA2 and gBRCA2 rate of at least 9.8%." (PMID 40046829, 2025). "There were 280 metastatic prostate cancer samples tested with 11 (4%) somatic BRCA2 and 7 (2.7%) somatic ATM identified with 1 somatic BRCA1." (PMID 40046829, 2025). "The importance of providing molecular information on the BRCA1 and BRCA2 genes is widely recognized, especially for patients with metastatic prostate cancer." (PMID 39335746, 2024). "The recent approval of olaparib has paved the way to precision medicine for the treatment of metastatic prostate cancer with PARP inhibitors in this subset of patients, especially in the case of BRCA1 or BRCA2 pathogenic/likely pathogenic variants." (PMID 38731844, 2024). "Based on this evidence, a referral for BRCA1/BRCA2 testing was proposed for men with metastatic prostate cancer." (PMID 37240284, 2023). "Conversely, XGBoost-derived models showed strong performance including an area under the curve of 0.99, 0.99 and 1.00 for identifying BRCA2, CDK12, and mismatch repair deficiency in metastatic prostate cancer." (PMID 36914848, 2023). "In metastatic prostate cancer, an expanded HRD panel included patients with mutations to BRCA1, BRCA2, ATM, FANCA, CHEK2, PALB2, NBN, or HDAC2." (PMID 35205643, 2022). "Tumor testing for BRCA1 and BRCA2 is recommended for patients with metastatic prostate cancer, also considering a broad panel to guide decisions and genetic counseling." (PMID 33625671, 2021). "Approximately 23% of metastatic prostate cancers harbor mutations in DNA-Damage Repair (DDR) genes, including BRCA2, BRCA1, ATM, CDK12, or PALB2 among others." (PMID 33625671, 2021).
metastatic prostate carcinoma (continued). "In one patient, we detected biallelic BRCA2 deletion via targeted and WES of ctDNA; tri-nucleotide mutational signature analysis revealed HRR-defect-associated signature 3 as one of the predominant signatures in this patient (12%), similar to BRCA2-deficient metastatic prostate cancer." (PMID 33420073, 2021). "Some, but not all, TNBC and early metastatic prostate cancers are associated with germline variants in BRCA1, BRCA2, and other genes involved in HR DNA repair." (PMID 38837893, 2024).
familial breast cancer (29 papers, 2006 to 2024). "Clinically, the patient was strongly suspected to have familial breast cancer due to BRCA1 or BRCA2 pathogenic variants." (PMID 39138315, 2024). "BRCA1 and BRCA2 are well-known genetic factors involved in DNA repair and are associated with a strong predisposition for early-onset familial breast cancer." (PMID 37483962, 2023). "Detection of a pathogenic BRCA2 variant in a patient with familial breast cancer, frequently associated with hormone receptor-positive breast carcinoma as reported in this case, led to a high level of confidence on which to base risk management in future." (PMID 32231682, 2020). "The inheritance of mutated suppressor genes, such as BRCA1 and BRCA2, is acknowledged as an etiological factor in hereditary breast carcinoma (HBC)." (PMID 31518337, 2019). "Germline mutations in the BRCA1 and BRCA2 genes are the most frequent known hereditary causes of familial breast cancer." (PMID 27149669, 2016). "In the model proposed in the present study, the classification of five types of cancers simultaneously was enhanced with ‘Non BRCA1/BRCA2 familial breast cancer’, also a class under study, yielding a recall value of 0.92 and precision of 0.89." (PMID 36401182, 2022). "Two TSGs, BRCA1 and BRCA2 (BReast CAncer), are responsible for 80-90% of cases of “single gene” hereditary breast carcinoma." (PMID 31518337, 2019). "Hereditary familial breast cancer tends to have an early onset, particularly in those with BRCA1/BRCA2 mutations." (PMID 28894168, 2017). "In familial breast cancer, BRCA1 and BRCA2 have been the primary targets in Latin American studies, and one of their main achievements is the detection of new variants only present in those populations." (PMID 33126731, 2020). "Importantly, the peripheral-blood expression patterns were predictive of familial breast cancer, independent of BRCA1/BRCA2 mutation status." (PMID 26538066, 2015).
invasive ductal carcinoma (27 papers, 2003 to 2026). "After Bonferroni correction, BRCA1 tumors were most frequently associated with invasive ductal carcinoma, whereas BRCA2 tumors were more frequently associated with ductal carcinoma in situ (p < 0.001)." (PMID 36905492, 2023). "A 47-year-old woman with a BRCA2 mutation developed a 4-mm-sized invasive ductal carcinoma (IDC) that was estrogen receptor (ER)-positive and human epidermal growth factor receptor (HER2)-negative." (PMID 30980249, 2019). "For BRCA2 mutated patients, 82% were invasive ductal carcinomas, 14% lobular invasive carcinomas and 4% were medular tumors." (PMID 27741520, 2016). "First, we analyzed the mRNA levels of AURKB in prostate adenocarcinoma patients and breast invasive ductal carcinoma patients with low mRNA levels of BRCA2 from cBioPortal." (PMID 37934606, 2024). "The mRNA levels of BRCA2 were significantly increased in patients with invasive ductal breast carcinoma and invasive lobular breast carcinoma, with fold changes of 3.214 and 2.124, and p values of 1.46 × 10−25 and 9.36 × 10−9, respectively." (PMID 35409110, 2022). "Lobular carcinoma (occurring in breast lobules) was the second most common subtype for BRCA2 carriers (8.4%), and medullary carcinoma (a subtype of invasive ductal carcinoma) for BRCA1 carriers (9.4%)." (PMID 32481735, 2020). "Invasive ductal carcinoma was the most prevalent histology in both groups; however, the distribution of tumor histology differed significantly between BRCA1 and BRCA2 mutation carriers (P = 0.002)." (PMID 30820924, 2019). "The majority of tumours were invasive ductal carcinoma in both BRCA2 (95.1 %) and BRCA1 (100 %) carriers." (PMID 26857456, 2016). "patient: BRCA2 c.7976G>A het, p.Arg2659Lys and RAD50 c.287T>C het, p.Val96Ala, which are pathogenic and VUS, respectively; the patient has been receiving treatment for Grade 3 triple negative, invasive ductal carcinoma as well, which was diagnosed at the age of 29 years." (PMID 39148954, 2024). "They observed frequent promoter hypermethylation of BRCA2, CDH13, MSH6, PAX5, PAX6, and WT1 genes in both DCIS and adjacent invasive ductal adenocarcinoma lesions." (PMID 40131297, 2025). "With regard to the histological tumor subtypes, of the 86 with invasive ductal carcinomas, 11 patients exhibited BRCA1 positivity and 6 patients exhibited BRCA2 positivity." (PMID 30713775, 2019). "Invasive ductal carcinoma was the most prevalent type in both BRCA1 and BRCA2." (PMID 30820924, 2019).